MMP2 (matrix metallopeptidase 2)
Diseases named in the same sentence as MMP2 in open-access papers (continued):
Sharing a sentence is not in itself a finding about the gene and the disease.
hepatocellular carcinoma (continued). "In hepatocellular carcinoma, SRPX2 knockdown suppressed pulmonary metastasis of hepatocellular carcinoma HCCLM3 cells in nude mice, which the mechanisms were through inhibiting FAK/AKT pathway-mediated MMP2/9 expression." (PMID 35935582, 2022). "In hepatocellular carcinoma (HCC) cell lines, the expression of MMP2 and MMP9 (enzymes that catalyze collagen hydrolysis) are upregulated after autophagy activation, which stimulates cell invasion." (PMID 35884904, 2022). "Our results suggested that the FAK/PI3K/AKT/mTOR pathway affects the activities and expressions of MMP-2 and MMP-9, further inhibiting the migration and invasion of hepatocellular carcinoma cells." (PMID 36483979, 2022). "For instance, tan IIA blocks the nuclear factor kappa-B (NF-κB) signaling pathway to inhibit the activity of MMP2 and MMP9, thereby preventing the metastasis and invasion of human hepatoma cells and hepatocellular carcinoma (HCC) cells." (PMID 36172186, 2022). "Next, HCCLM3 were treated with heparin sodium, which can bind to HSPGs on hepatoma cells and block the binding of CSP I-plus to the surface of hepatoma cells, and analyzed the expression both mRNA and protein levels of VEGFA and MMP2, integerβ1, E-cadherin." (PMID 36419008, 2022). "It has been found that BITC treatment inhibited the MMP-2/-9 protein expression in a dose-dependent manner, whereas it increased TIMP-2 expression in SK-Hep-1 human hepatoma cells." (PMID 36430307, 2022). "SRPX2 expedites hepatocellular carcinoma by targeting the FAK/AKT pathway and regulating the expression of MMP2/9." (PMID 36385962, 2022). "The inhibition of the STAT3 and MMP2/MMP9 signaling pathway reversed EMT and inhibited the migration and invasion of hepatocellular carcinoma cells." (PMID 34876128, 2021). "Bicuculline can effectively inhibit the migration and invasion of human hepatocellular carcinoma MHCC97-H cells which is related to the downregulation of VEGF, MMP-2, and MMP-9 gene expression and inhibition of JAK2/STAT3 signaling pathway activation." (PMID 34497656, 2021). "Knockdown of TPX2 suppresses the invasion and proliferation of hepatocellular carcinoma cells via the deactivation of AKT signaling and suppression of MMP-2 and MMP-9 gene expression." (PMID 33531976, 2021). "Cav-1 expression has previously been reported to lead to activation of MMP2 and MMP9 promoting invasion in hepatocellular carcinoma cell lines and non-small lung carcinoma." (PMID 34490102, 2021). "Given the critical roles of matrix metalloproteinases (MMPs) in the migration and metastasis of tumour cells, the levels of MMP-2 and MMP-7 were examined after exposure to protopine in liver carcinoma cells." (PMID 34315493, 2021). "MMP2 and MMP9 are predictors of liver cancer recurrence and are highly expressed in invasive hepatocellular cancer (HCC) cells." (PMID 35011007, 2021). "In hepatocellular carcinoma, lncRNA DLX6‐AS1 acted as a sponge of miR‐203a that also specifically targeted MMP‐2." (PMID 32951317, 2020). "Autophagy has also been reported to promote invasion by activating Epithelial Mesenchymal Transition of hepatocellular carcinoma cells, by promoting secretion of factors like IL6, MMP2 and by activating the MAP kinase signaling pathway in glioblastoma cells." (PMID 30944042, 2019). "We found that copper can also up-regulate MMP-2 and MMP-14 expression in human hepatocellular carcinoma cell HUH-7 and human pancreatic cancer cell MIA PaCa-2." (PMID 28881637, 2017). "NDRG2 overexpression inhibits the expression of MMP2 and MMP9 in clear cell renal cell carcinoma (CCRCC) and hepatocellular carcinoma (HCC)." (PMID 26506239, 2016). "Both MMP-2 and MMP-9 have been shown to be up-regulated after radiation in hepatocellular carcinoma and glioblastoma." (PMID 27835571, 2016).
hepatocellular carcinoma (continued). "The metastasis of HCC involves in elevating expression of metastasis‐related molecules, including keratin 19 (K19) 9, epithelial cell adhesion molecules (EpCAM) 10, matrix metalloproteinase 2/9 (MMP2/9) 11 and CXCR4 12 in hepatoma cells." (PMID 26756858, 2016). "High expression of MMP-2 and MMP-9 was found to be associated with time to tumor recurrence in HCC patients after surgical resection, while decrease the expression level of MMP-2 and MMP-9 resulted in the inhibition of invasion and metastatic capabilities of hepatocellular carcinoma cells." (PMID 26177288, 2015). "In hepatocellular carcinoma cells, JWA down-regulation enhances cancer progression through the induction of MMP-2 activity and elevated FAK expression." (PMID 26046674, 2015). "Twist also enhanced hepatocellular carcinoma EMT and invasion through activating matrix metalloproteinase (MMP)-2 and MMP-9 expression." (PMID 25868853, 2015). "Based on the expression status of GRP78, MMP-2, MMP-9, MMP-14 and TIMP-2 in hepatocellular carcinoma cell lines SMMC7721 and HepG2, we choose SMMC7721 to establish the in vitro invasion model for further research." (PMID 22546345, 2012). "In this study, we show that knockdown of GRP78 reduces the invasiveness and metastasis in hepatocellular carcinoma cells SMMC7721, and we identify a molecular mechanism involving FAK-Src-JNK-c-Jun-MMP2 signaling pathway in these effects." (PMID 22546345, 2012). "According to the expression levels of GRP78, MMP-2, MMP-9, MMP-14 and TIMP-1 in hepatocellular carcinoma cell lines SMMC7721 and hepG2, we used SMMC7721 as the in vitro invasion model for further functional analysis." (PMID 22546345, 2012). "We choose hepatocellular carcinoma cell line SMMC7721 for the establishment of in vitro invasion and metastasis model according to the expression levels of GRP78, MMP-2, MMP-9, MMP-14 and TIMP-2." (PMID 22546345, 2012). "Osteopontin up-regulates MMP-2 through activating the SDF-1α/CXCR4 axis, mediated by binding to integrin αvβ3 and CD44v6 and activating the PI3K/Akt and JNK pathways in hepatocellular carcinoma cells (HepG2 and SMMC7721)." (PMID 21909361, 2011). "Specially for hepatoma cell invasion, MMP-9 has been shown to be more likely to participate in hepatoma cell invasion than MMP-2 for its destruction of tumor capsule." (PMID 21738655, 2011). "Similarly, in hepatocellular carcinoma, caudatin-induced inhibition of Wnt/β-catenin signaling suppressed COX-2 (Cyclooxygenase-2) and MMP-2/MMP-9 expressions to favor inhibited metastasis (Row 2)." (PMID 40959450, 2025). "Likewise, upregulated exo-circ_ 0039411 derived from hepatocellular carcinoma (HCC) enhances cell invasion and migration via sponging miR-136-5p and facilitating MMP2 expression." (PMID 39484707, 2024). "Moreover, chlorogenic acid exhibited potent in vitro and in vivo antiproliferative activity against hepatocellular carcinoma by inducing cell cycle arrest in the S phase, reducing the phosphorylation of ERK1/2, and decreasing MMP-2 and MMP-9 expression." (PMID 39478959, 2024). "The strong inhibitory effect of C-phycocyanin contained in Spirulina platensis protein extracts on the activity of human gelatinases MMP-2 (by 55.13%) and MMP-9 (by 57.9%) as well as the drop in the mRNA expression of both gelatinases has been documented in the hepatocellular cancer cell line HepG2." (PMID 39458962, 2024). "RhoGDI2 has been shown to be upregulated in hepatocellular carcinoma (HCC) cells where its overexpression increased their rates of proliferation and invasion, via activating the PI3K/Akt pathway and increasing the levels of MMP2 and MMP9 (consistent to PDAC)." (PMID 36835422, 2023). "Among them, MMP2 and MMP9 are involved in the metastasis of hepatocellular carcinoma." (PMID 35383533, 2022).
hepatocellular carcinoma (continued). "It was observed in hepatocellular carcinoma that IL-17-driven AKT signaling activation resulted in IL-6 production, which in turn activated JAK2–STAT3 signaling and subsequently upregulated its downstream targets, IL-8, MMP2, and VEGF." (PMID 35884700, 2022). "Moreover, HMGB1 promoted hepatocellular carcinoma progression partly by enhancing the ERK1/2 and NF-κB pathways, upregulating MMP-2, and downregulating p21 via an ERK/c-Myc pathway." (PMID 35610613, 2022). "MMP-2 is involved in CCL3-dependent cell invasion in oral squamous cell carcinoma and chondrosarcoma, whereas MMP-9 is involved in CCL3-dependent cell invasion in hepatocellular carcinoma and oral squamous cell carcinoma." (PMID 32457351, 2020). "In addition, AIM showed inhibitory effects on the expression of MMP-2 and MMP-9 in MCF-7 cells, which is similar with the previous studies demonstrating the inhibitory effects of AIM on the expression of MMP-2 and MMP-9 in hepatocellular carcinoma cells." (PMID 32455624, 2020). "Rab11 upregulates MMP2 and activates AKT signaling in hepatocellular carcinoma, suggesting the function of Rab11a might share some similarities." (PMID 33178272, 2020). "Its overexpression promotes cell proliferation and invasion by influencing focal adhesion kinase (FAK) in hepatocellular carcinoma and extracellular signal‐regulated kinase (ERK)/matrix-metallo proteinase-2 (MMP‐2) signaling pathways in oral cancer, respectively." (PMID 31426400, 2019). "In hepatoma cells, expression of MT1-MMP, MMP-2, and MMP-9 facilitates stromal invasion." (PMID 30970564, 2019). "The mRNA levels of both MMP-2 and MMP-14 in human hepatocellular carcinoma (HCC) cell SMMC-7721 were up-regulated by Cu2+ in a concentration dependent manner, whereas the mRNA levels for other tested MMPs (MMP-1, MMP-3 and MMP-9) were not changed when treated with up to 40 μM Cu2+." (PMID 28881637, 2017). "One study indicated that low dose of SHK (4 μM) (around 1.33 μg/mL) did not influence the survival of hepatocellular carcinoma cells but inhibited the migratory ability through downregulation of MMP-2 and -9 and vimentin expressions." (PMID 25737737, 2015). "Our study demonstrated the effectiveness of MMP2 aCPPs as a non-viral method of introducing hTERT siRNA into hepatoma cells to suppress the expression of hTERT." (PMID 25671640, 2015). "Our in vivo results revealed that bufalin was able to decrease MMP-2 and MMP-9 expression levels in a dose-dependent manner, whereas our previous in vitro experiments show that bufalin is able to decrease MMP-2 and MMP-9 expressions in hepatoma cell lines." (PMID 24581171, 2014). "Human hepatocellular carcinoma cell line SMMC7721 and HepG2 were cultured in DMEM supplemented with 10% FBS, RT-PCR and western blot were used to detect the endogenous expression of GRP78, MMP-2, MMP-9 and TIMP-2 in SMMC7721 and HepG2." (PMID 22546345, 2012). "A recent study found that silencing β-catenin expression by RNA interference could inhibit angiogenesis-related gene expression (e.g., MMP9, MMP2, and VEGF) in hepatocellular carcinoma cells." (PMID 22957092, 2012). "In an animal model, the administration of black-tea polyphenon-B significantly reduces the incidence of dimethylaminoazobenzene (DAB)-induced hepatomas as evidenced by modulation of RECK, matrix metalloproteinase (MMP)-2, MMP-9, and the tissue inhibitor of matrix metalloproteinase-2." (PMID 22428065, 2012). "Our findings demonstrated the potential of genipin in suppressing hepatocellular carcinoma metastasis, and p38/TIMP-1/MMP-2 pathway may be involved as the key mechanism of its anti-metastasis effect." (PMID 23029478, 2012). "Here we are going to determine whether GRP78 knockdown affect the ECM degradation and the role of MMP-2 and MMP-9 in these process in hepatocellular carcinoma cells." (PMID 22546345, 2012).
hepatocellular carcinoma (continued). "TIMP-1 was reported to inhibit both MMP-2/9 activities in line, therefore the inhibition of MMP-2 activities in human hepatocellular carcinoma cells exposed to genipin may be attributable to up-regulation of TIMP-1." (PMID 23029478, 2012). "Thus, our findings suggest that miR-29a promotes hepatoma cell migration through targeting PTEN involving the activation of phosphorylated Akt and MMP-2." (PMID 21573166, 2011). "In experiments with human hepatocellular carcinoma (HCC) cell lines HepG2 and SMMC-7721, treatment with varying concentrations of ART resulted in a decreased expression of MMP2 and an upregulation of TIMP2, which is an inhibitor of MMP2." (PMID 40001571, 2025). "Besides, literature reports that CCR4 can aggravate hepatocellular carcinoma malignancy and facilitate hepatocellular carcinoma cell metastasis via activating ERK/AKT/MMP2 pathway and CCR4 can promote colorectal cancer metastasis via activating ERK/NF-κB/MMP13 pathway." (PMID 39473097, 2025). "Finally, sinapine thiocyanate from SS significantly decreases the protein expression of PTGS1, PTGS2, Bcl-2, MMP-2 and MMP-9 and increases the protein expression of Bax to prohibit the proliferation, migration and invasion of hepatocellular carcinoma cells in SMMC-7721." (PMID 37124205, 2023). "In hepatocellular carcinoma (HCC), B7-H3 knockdown upregulated E-cadherin expression but inhibited AKT phosphorylation, VE-cadherin expression and MMP2/9 activation in HCC cell lines, suggesting a PI3K/AKT/MMP pathway for B7-H3-mediated MMP activation." (PMID 36284349, 2022). "Our previous study also revealed that MTA2 is overexpressed in hepatocellular carcinoma (HCC), and MTA2 knockdown reduces the mestastasis of HCC cell lines by inhibiting MMP2 expression." (PMID 33958583, 2021). "In Apicidin-resistant HA22T hepatocellular carcinoma cells (HCC), the WNT/β-catenin and MMP2 are often activated." (PMID 32365809, 2020). "Particular attention has been paid to the imbalance between MMP-2 and TIMP-2 in hepatocellular carcinoma (HCC), and cervical, bladder, breast, and oral cancers." (PMID 32751899, 2020). "In hepatocellular carcinoma (HCC), upregulation of the EMT-TF Snail not only repressed E-cadherin transcription but also increased expression of MMP-1, MMP-2, MMP-7, and MT1-MMP leading to accelerated invasion." (PMID 31540068, 2019). "Studies in hepatocellular carcinoma and glioblastoma cell lines have shown that the activation of the PI3K/Akt pathway and subsequent NF-kB or mTOR activation upon radiation leads to the secretion of matrix metalloproteinases (MMP), mainly MMP-2 and MMP-9, and consequently to enhanced cell invasion." (PMID 27835571, 2016). "For example, mTOR signaling may be activated by the upregulation of MMP-9 but not by that of MMP-2 in hepatocellular carcinoma." (PMID 26202311, 2015). "According to previous reports, miR-29b suppresses angiogenesis, invasion, and metastasis by inhibiting MMP-2 expression in hepatocellular carcinoma; however, to our knowledge, no study has examined the relationship between miR-29 and BCL2L2 expression and their effect on GBM cell phenotype." (PMID 26155940, 2015). "Taken together, these results demonstrated that sinulariolide could inhibit hepatocellular carcinoma cell migration and invasion and alter HA22T cell metastasis by reduction of MMP-2, MMP-9, and uPA expression through the suppression of MAPKs, PI3K/Akt, and the FAK/GRB2 signaling pathway." (PMID 26204832, 2015). "In a cell line of hepatocellular carcinoma, TLR-9 activation increases proliferation and inflammation by up-regulating IL-8, IL-1, IL-6, inhibits apoptosis and in esophageal cells stimulates invasion by inducing the expression of matrix metalloproteinase 2 (MMP-2), MMP-7 and cyclooxygenase-2 genes." (PMID 28548068, 2014).
hepatocellular carcinoma (continued). "Furthermore, after treatment with baicalein for 24 hours, there was a decrease in the levels of matrix metalloproteinase-2 (MMP-2), MMP-9 and urokinase-type plasminogen activator (u-PA) expression as well as proteinase activity in hepatocellular carcinoma MHCC97H cells." (PMID 24039823, 2013). "Furthermore, since the basal levels of MMP-2 were dominantly and significant suppression of genipin on MMP-2 activity could be found in HCC cells, we concluded that genipin may target on MMP-2 majorly, which contributes to the anti-metastatic effect of genipin in hepatocellular carcinoma." (PMID 23029478, 2012). "This may indicate that genipin could downregulate the MMP-2 activity by inhibiting its cleavage activation but not suppressing its expression in hepatocellular carcinoma cells." (PMID 23029478, 2012). "To further elucidate the role of the SDF-1α/CXCR4 axis in human hepatocellular carcinoma, we detected the expression and activity of MMP-2 induced by 50 nM rhOPN in the presence or absence of SDF-1α neutralizing antibody, CXCR4 inhibitor 12G5, or CXCR4 inhibitor AMD3100." (PMID 21909361, 2011). "For instance, the kinase IGF1R and protease MMP2 were involved in 650 cases of motif V. MMP2 is located in the downstream of IGF1R-induced signaling pathway, and the inhibition of IGF1R will affect the dissemination of hepatocellular carcinoma (HCC) cells." (PMID 26853265, 2016). "Through the regulation of matrix metalloproteinases (MMP-2 and MMP-9) and the upregulation of E-cadherin expression, while downregulating N-cadherin and vimentin, RA also prevented the growth, invasion, and metastasis of hepatocellular carcinoma (HCC) cells in male BALB/c nude mice." (PMID 40427522, 2025). "The aim of the present study was to investigate the potential roles of the androgen receptor (AR) and matrix metalloproteinase (MMP)-2 and MMP-9 in hepatocellular carcinoma (HCC) tissues and whether their expression could be used as a predictor of the invasion and stage of cancer." (PMID 25667651, 2015). "In hepatocellular carcinoma cells, Grp78 knockdown inhibited ECM degradation and the decreased activity and expression of MMP-2, but not MMP-9 contributed largely to this impact." (PMID 22546345, 2012). "Similarly, in hepatocellular carcinoma (HCC), miR-21 derived from the tumor reduces PTEN levels, leading to the activation of the PDK1/AKT signaling pathway and an increase in the expression of VEGF, MMP2, MMP9, βFGF, and TGF-β in CAFs, thereby promoting angiogenesis." (PMID 37605155, 2023).